AR (androgen receptor)
Diseases named in the same sentence as AR in open-access papers (continued):
Sharing a sentence is not in itself a finding about the gene and the disease.
prostate carcinoma (continued). "Canine PC is an interesting model to use in comparative prostate cancer research; however, it is important to note the differences, including those reported for the AR gene." (PMID 30925701, 2019). "As already mentioned, one of the most important hormone-inhibition-escape-strategy adopted by prostate cancer cells is the alternative splicing of the AR which results in the expression of different alternative AR-Vs." (PMID 30642011, 2019). "A 6-d-long treatment with IRC117539 dramatically reduced the survival of cultured LNCaP, VCaP, and 22Rv1 prostate cancer cell lines whose proliferation was previously reported to be AR-driven." (PMID 31431473, 2019). "Therapeutic strategies to target AR antagonist resistance are urgently needed to improve outcomes for men with this lethal form of prostate cancer." (PMID 31228231, 2019). "We have recently shown that ERG regulates intra-tumoral androgen synthesis and thereby facilitates AR function in prostate cancer cells." (PMID 31638934, 2019). "AR signaling plays a crucial role in cell proliferation, survival, and invasion in prostate cancer development." (PMID 31395805, 2019). "Decursin is a coumarin from AGN or KMKKT root ethanolic extract, known as an antiandrogen and AR compound that can suppress PSA expression after 48-h exposure on prostate cancer cells (IC50 = 0.4 μg/mL)." (PMID 31261861, 2019). "Recently, Sigma1 was found to regulate aberrant androgen receptor (AR) activity and stability in prostate cancer cells." (PMID 31695608, 2019). "We detected similar splicing switches for 35/44 of these skipped exons after jointly depleting ESRP1 and 2 from the AR-positive CWR22 RV1 prostate cancer cell line." (PMID 31478829, 2019). "circSMARCA5 is an androgen-induced circRNA in prostate cancer, and the activation of androgen receptor pathway is a common driver of prostate cancer progression." (PMID 31662805, 2019). "CWP232291 induces apoptotic cell death and modulates the WNT pathway, resulting in suppression of β-catenin and AR in prostate cancer cells." (PMID 31387608, 2019). "Current therapies for prostate cancer target preferentially partially differentiated, AR-dependent and proliferating tumor cells that constitute the bulk of the tumor mass in locally advanced and metastatic tumors." (PMID 31143708, 2019). "Examples of SNPs and aberrant enhancer and super-enhancer activity leading to transcription dysregulation in prostate cancer, for instance due to aberrant expression of the AR or of the c-Myc gene, are detailed below." (PMID 31200487, 2019). "AR (androgen receptor)-signaling is particularly important in prostate cancer, however, AR is also expressed in up to 90% of ER+ BRCA, and to a lesser degree, in HER2 amplified tumors." (PMID 31238876, 2019). "We independently treated the AR reliant prostate cancer cell line LNCaP with enzalutamide (ResA) and RD-162 (ResB) to generate two distinct anti-androgen resistant cell lines." (PMID 31551480, 2019). "There is an implicit understanding supported by recent studies that there is a benefit from molecular characterization of AR in CTCs in prostate cancer." (PMID 31289619, 2019). "It was also reported that specific 5′ tRNA halves were produced more abundantly in androgen receptor (AR)-positive prostate cancer and in estrogen receptor (ER)-positive breast cancer than in the respective negative forms." (PMID 31616639, 2019). "Signaling through the androgen receptor (AR) is important in prostate cancer, even in the advanced castrate-resistant prostate cancers." (PMID 30781847, 2019). "In two androgen receptor (AR)-positive prostate cancer cell lines, C4-2B and LNCaP, we first validated ERβ’s tumor suppressor activity indicated by the inhibition of cell proliferation and repression of MYC expression." (PMID 30979864, 2019). "In particular, BRM is required for proliferation of androgen-dependent prostate cancer and regulates androgen receptor (AR) target genes expression." (PMID 31722744, 2019).
prostate carcinoma (continued). "Amplification and overexpression of the AR gene are by far the most frequent resistance mechanisms observed in prostate cancer patients treated with drugs that suppress androgen signaling." (PMID 31200487, 2019). "Prostate cancer cells rely on androgens for proliferation and survival, via activation of AR-FL and its targeted genes." (PMID 30664691, 2019). "In particular, extensive research focusing on SRs in subfamily 3 including AR and other AR-mimic SRs should be required as these NRs are considered to play critical roles in prostate cancer pathogenesis." (PMID 31212954, 2019). "Prostate cancer cells remain dependent on the androgen receptor (AR) even in the castration resistant stage (with the rare exception of neuroendocrine tumor)." (PMID 31819114, 2019). "In support of this observation, the androgen receptor target gene PSA remains expressed in recurrent prostate cancer tissues, despite the castrate levels of androgens in serum." (PMID 31552182, 2019). "Here we show that prostate cancers can amplify AR output through increased expression of the dual AR/ER coactivator GREB1, in the absence of genomic AR alterations." (PMID 30644358, 2019). "The role of FGF9 and AR in the mechanism of prostate cancer pathogenesis, in view of its resistance to castration, has been investigated." (PMID 31137764, 2019). "Specifically in prostate cancer, androgens functioning through the androgen receptor (AR) are central to both initiation and disease progression." (PMID 30742096, 2019). "Other mechanisms of action of polyphenols include the inhibition of key molecules involved in alternative activation pathways of AR in prostate cancer, such us PI3K/Akt, NF-κB, or MAPK." (PMID 30823649, 2019). "AR has an essential role in prostate cell proliferation and hence DDB2 can inhibit cell growth in AR-expressing prostate cancer cells." (PMID 30923324, 2019). "PlexinB1 and its ligand Sema3C have been shown to promote resistance to androgen receptor pathway inhibition in prostate cancer treatment." (PMID 31861264, 2019). "Hormonal manipulation in men with prostate cancer can be achieved by reducing the availability of androgens and/or interference with their functions through the androgen receptor (AR) pathway." (PMID 30800682, 2019). "Androgens and their intracellular target, the androgen receptor (AR), are established drivers of prostate cancer initiation, development and progression." (PMID 31628408, 2019). "We showed for the first time that ERG transcription factor regulates androgen biosynthesis and subsequent AR activation in prostate cancer cells." (PMID 31638934, 2019). "LBCS overexpression decreases, whereas LBCS knockdown increases, the traits of castration resistance in prostate cancer cells under androgen ablated or AR blocked condition." (PMID 31221168, 2019). "AR regulates male sexual maturation, maintenance of normal prostate function, prostate carcinogenesis, and prostate cancer (PCa) progression." (PMID 31429764, 2019). "In the androgen-sensitive (androgen-dependent) prostate cancer cell lines, the downregulation in androgen receptor (AR) expression reduced AR-mediated transcription and cell growth." (PMID 31137764, 2019). "Nevertheless, some prostate cancers become “androgen refractory” during ADT, probably due to mutations or amplification of the AR gene." (PMID 30823649, 2019). "The androgen receptor (AR) is known to be involved in the pathogenesis and progression of prostate cancer." (PMID 31689899, 2019). "In all prospective prostate cancer samples, a SCAA was identified mainly being amplification of the AR gene which is a well-known resistance mechanism in 50% of castration-resistant prostate cancers." (PMID 30858924, 2019). "HSP90 is overexpressed in prostate cancer; co-treatment of prostate cancer cells with AR antagonist Enzalutamide and a HSP90 inhibitor induces an increased rate of cell death due to a synergistic reduction of AR protein induced by the two drugs." (PMID 31366128, 2019).
prostate carcinoma (continued). "Similar to the current approach of inhibiting prostate cancer by targeting AR we have also observed the SeNP induced down-regulation of AR and the induction of cell death." (PMID 32010628, 2019). "N-Myc overexpression, whatever in PCA or in CPRC stage, shuts down AR signaling that is required for prostate cancer growth, and as a consequence should benefit the N-Myc overexpressed prostate tumors to AR-targeted therapies." (PMID 30657058, 2019). "Since CDK5 regulates both STAT3 and AR activation, it is important to further understand the detailed mechanism of this regulation in prostate cancer cells." (PMID 31395805, 2019). "In line with our findings, AR in the tumor stroma has been consistently found to be a predominant factor in the prognosis of prostate cancer." (PMID 30925918, 2019). "In prostate carcinoma models, HDACi have been shown to have an opposite effect of downregulating androgen receptor (AR) expression and AR-dependent signaling." (PMID 30841549, 2019). "Although this is a small dataset, the results indicate that the AR transcriptional heterogeneity we observe in prostate cancer cell lines is present in patient samples." (PMID 30644358, 2019). "This review focuses on the emerging roles of splicing factors in prostate cancer progression and AR signaling." (PMID 30939845, 2019). "Pyk2 activates ribosomal S6K1, regulates androgen receptor (AR) function, and enhances prostate cancer cell growth and survival." (PMID 31368612, 2019). "Prostate cancer is a common carcinoma in males, the development of which involves the androgen receptor (AR) as a key regulator." (PMID 31405024, 2019). "Clinical and experimental data widely suggest that AR signalling is the master regulator of prostate cancer growth and progression." (PMID 30832393, 2019). "The PI3K/Akt pathway is a well-established oncogenic pathway in human cancer and is involved in resistance to AR-targeted therapy in prostate cancer." (PMID 31761786, 2019). "Several scientific studies demonstrated that curcumin and its analogues exert anti-cancer effects on prostate cancer models including its effects on androgen receptor (AR) signaling and numerous downstream targets." (PMID 30720759, 2019). "The interaction between androgen receptor (AR) and coactivator proteins plays a critical role in AR-mediated prostate cancer (PCa) cell growth, thus its inhibition is emerging as a promising strategy for PCa treatment." (PMID 31370197, 2019). "The improvement of the sensitivity anf the precision of the cfDNA techniques allowed the unique opportunity of monitoring in the time during treatment the genomic profiling of prostate cancer patients undergoing treatment with AR antagonists." (PMID 31366128, 2019). "Phosphorylation of AR on serine or tyrosine residues is correlated with various biological processes such as transcriptional regulation, activation, degradation, or prostate cancer growth." (PMID 31395805, 2019). "TRIM24 levels increase during prostate cancer progression, and the AR/TRIM24 gene signature as well as TRIM24 levels predict disease recurrence." (PMID 31366128, 2019). "While the involvement of abnormal Androgen Receptor (AR) signalling in prostate cancer is well established, there is growing evidence that it also plays a role in various other malignancies." (PMID 30979711, 2019). "The high definition-CTC (HD-CTC) is an exemplary technology that facilitates real-time single-cell characterization of morphometric (i.e., cell roundness, cell area, AR subcellular localization) and protein expression changes in AR for prostate cancer." (PMID 31635038, 2019).
prostate carcinoma (continued). "Androgen receptor (AR) signalling is a key prostate cancer (PC) driver, even in advanced ‘castrate-resistant’ disease (CRPC)." (PMID 31043708, 2019). "Androgen receptor signaling is the primary driver of prostate cancer, and subsequently, medical castration with androgen deprivation therapy is the backbone of all treatments in men with metastatic prostate cancer." (PMID 31035489, 2019). "Abnormalities in androgen receptor (AR) signaling pathway members are very frequent in prostate cancer." (PMID 31366128, 2019). "Instead, olaparib treatment reduced AR protein levels only in BRCA2-knockdown prostate cancer cells, and the addition of 6-TG had a synergic effect in reducing AR levels." (PMID 31284411, 2019). "β-catenin forms a complex with AR and through this mechanism augments AR signaling in prostate cancer." (PMID 31366128, 2019). "Analysis of clinical datasets supported a molecular shift at various stages of prostate cancer progression, indicating the existence of a consistent correlation between β-catenin and AR expression." (PMID 31366128, 2019). "In androgen-sensitive LNCaP prostate cancer cells, immunoprecipitation of endogenous AR after DHT treatment or Ack1 expression demonstrated that association between AR and SLIRP is inhibited by DHT or Ack1 activation." (PMID 31819114, 2019). "KDM4B expression is also directly induced by androgens via the androgen receptor to promote a more aggressive prostate cancer phenotype." (PMID 30759871, 2019). "In prostate cancer, cytoplasmic dynein promotes AR transport to the nucleus, resulting in prostate cancer progression." (PMID 31249807, 2019). "In advanced prostate cancer (PCa), androgen receptor (AR) pathway inhibition (ARPI) induces profound and sustained responses." (PMID 31127190, 2019). "Actually, the mechanisms of resistance to AR blockade have been extensively characterized in prostate cancer." (PMID 31527644, 2019). "It is well established that AR signaling plays a central role in the initiation and progression of prostate cancer." (PMID 31877956, 2019). "In advanced prostate cancer, DNA-PKcs coactivates the androgen receptor (AR), promoting metastatic phenotypes." (PMID 31380275, 2019). "Androgens stimulate androgen receptor (AR) signalling in prostate cancer cells to control transcription, including of genes that regulate the cell cycle, central metabolism and biosynthesis, as well as housekeeping functions." (PMID 31478829, 2019). "On an independent experiment with the same prostate cancer (PCa) cell line, AR pathway activity increased after DHT treatment and decreased again when DHT was combined with the anti-androgen drug bicalutamide." (PMID 30733525, 2019). "The blocking of CDK5 activity by its small interfering RNAs (siRNA) or Roscovitine, a pan-CDK inhibitor, reduces the cellular AR protein level and triggers the death of prostate cancer cells." (PMID 31395805, 2019). "Around 10% of all patients diagnosed with prostate cancer progress into AR independent mCRPC with a two-year survival rate." (PMID 31771198, 2019). "Different attempts have been made to target AR expression and signaling for the treatment of prostate cancer." (PMID 32010628, 2019). "Abiraterone also antagonizes androgen receptor (AR), which plays a crucial role in the progression of prostate cancer." (PMID 31827406, 2019). "The critical role of the androgen receptor (AR) in prostate cancer cell proliferation and survival is the enduring basis for treating advanced prostate cancer with drugs that block AR function or androgen biosynthesis." (PMID 31083651, 2019). "In another study, Rg3 displayed antitumor activity in LNCaP cell line via the down-regulation of the androgen receptor (AR) and other prostate cancer biomarkers." (PMID 31277214, 2019).
prostate carcinoma (continued). "Inhibition of GATA2 by small-molecule compounds is a potential strategy in blocking AR expression and signaling in castration-resistant prostate cancer." (PMID 31552182, 2019). "Therapy of advanced prostate cancer is based on interference with androgen receptor (AR) signaling and androgen deprivation therapy (ADT) has been firmly established as the principal therapeutic approach." (PMID 31289619, 2019). "In accordance with previous reports in prostate cancer fibroblasts, we observed that AR is expressed in breast cancer stromal cells." (PMID 31817155, 2019). "AR coregulators have been shown to be influential in the progression of prostate cancer to castration resistance." (PMID 31253147, 2019). "Our previous work identified UXT as a transcription factor that directly binds to the AR N-terminus and modulates AR transcriptional activity in prostate cancer cells." (PMID 30774773, 2019). "The metabolism operant in AR-driven prostate cancer is peculiar because is mainly fueled by lipogenesis and less by glycolysis and is more reliant on oxidative phosphorylation thgan most other solid tumors." (PMID 31366128, 2019). "Relationships between transcription factors and DUBs can be complex: for example USP7, USP12, USP14, USP22 all appear to regulate the stability and function of androgen receptor (AR) in prostate cancer." (PMID 30854565, 2019). "Here, we report an unexpected role for TLE3 in regulating AR-mediated repression of the GR locus affecting AR inhibitor sensitivity in prostate cancer cells." (PMID 31855178, 2019). "Our study showed the increased phosphorylation of AR on the Ser-81 site, even in androgen-independent LNCaP prostate cancer cells." (PMID 31395805, 2019). "JMJD3 also activated key oncogenes in gene of phosphate and tension homology deleted on chromosome ten (PTEN) and androgen receptor (AR) pathways participated in prostate cancer." (PMID 31701394, 2019). "Honokiol showed to be highly effective in dose-and time-dependently inhibit the viability of LNCaP and C4-2, cutting the protein level of AR, androgen-stimulating nuclear translocation of AR, and transcriptional activity of AR in prostate cancer cells lines." (PMID 31261861, 2019). "Transcriptomje studies show an overexpression of genes involved in AR activity in African Carribbean prostate cancers and of PVT1, a long non-coding RNA located at 8q24." (PMID 31366128, 2019). "When the levels of the GREB1 protein were experimentally decreased in prostate cancer cells with a high androgen receptor output, the cells became less resistant to the antiandrogen drug." (PMID 30644358, 2019). "Intratumoral androgen synthesis is the mainstay for AR signaling in castration resistance prostate cancer progression." (PMID 31638934, 2019). "The levels of androgen and its receptor (androgen receptor, AR) play essential roles in the early development of prostate cancer." (PMID 31395805, 2019). "Development of this type of invasive prostatic carcinoma in this model suggests a collaborative role of AR activation and p16Ink4a deletion in prostate cancer initiation and progression." (PMID 30677079, 2019). "In prostate cancer, there are evidences that seem to correlate cyclins expression to AR expression, radio-resistance and hormone inhibition resistance." (PMID 30642011, 2019). "Using two AR-positive prostate cancer cell lines, C4-2B and LNCaP, we demonstrated that ERβ also has a suppressive activity in these cell lines, as indicated by SRB and colony formation assays." (PMID 30979864, 2019). "Bioresponse formulated 3,3′-diindolylmethane (BR-DIM) decreases androgen receptor (AR) variants and AR3 expression in prostate cancer." (PMID 31208095, 2019). "Adding the OncoScan SCNA analysis to the cfDNA profiling did not increase the number of positive findings in the prospective cohorts and only included one more patient (P35, prostate cancer with AR amplification) in the retrospective cohort." (PMID 30858924, 2019).